FBXL7 (F-box and leucine rich repeat protein 7)
Diseases named in the same sentence as FBXL7 in open-access papers (continued):
Sharing a sentence is not in itself a finding about the gene and the disease.
FBXL7 also shares sentences with these, for which no sentence is quoted: lung squamous cell carcinoma (2 papers); metabolic syndrome (2); Alzheimer disease (1); Arthritis (1); cervical squamous cell carcinoma (1); colon adenocarcinoma (1); colon cancer (1); gastroesophageal reflux disease (1); head and neck cancer (1); infectious disease (1); liver cancer (1); mesothelioma (1); nasopharyngeal carcinoma (1); prostate adenocarcinoma (1); rectum adenocarcinoma (1); rhinitis (1); stomach cancer (1); thyroid cancer (1).